LINC03145 (long independently transcribed non-coding RNA 3145)
Synonyms: CRART16
Gene: Long non-coding RNA gene on chromosome 16 (47,004,513 to 47,035,819, forward strand). Ensembl gene ENSG00000259821.
Diseases named in the same sentence as LINC03145 in open-access papers:
LINC03145 is named in the same sentence as 4 diseases in open-access papers, as found by Europe PMC text mining. Sharing a sentence is not in itself a finding about the gene and the disease.
LINC03145 shares sentences with these, for which no sentence is quoted: tumor (2 papers); cancer (1); gastric cancer (1); gastric tumor (1).